CLEC18A (C-type lectin domain family 18 member A)
Description:
Binds polysaccharides in a Ca(2+)-independent manner with a preferentially binding to fucoidan, beta-glucans and galactans.
Synonyms: MRLP2; MRCL; MRCL1
Tractability: Antibody: UniProt places it where antibodies can reach, with high confidence; UniProt predicts a signal peptide or a membrane-spanning region; its Gene Ontology location is reachable by antibodies, with medium confidence.
Gene: Protein-coding gene on chromosome 16 (69,950,705 to 69,964,452, forward strand). Ensembl gene ENSG00000157322.
Subcellular location: Secreted; Endoplasmic reticulum; Golgi apparatus; Endosome
Gene Ontology:
Molecular function: polysaccharide binding; protein binding
Cellular component: extracellular region; endoplasmic reticulum; endosome; Golgi apparatus
Genetic constraint (gnomAD): Loss-of-function variants: 5 observed, 16.68 expected, observed/expected ratio (o/e) 0.3, 90% interval 0.16 to 0.63. The synonymous counts are far from expectation, so gnomAD's model fits this gene poorly and the ratio says little. Missense variants: 82 observed, 158.56 expected, observed/expected ratio (o/e) 0.52, 90% interval 0.43 to 0.62. Synonymous variants: 29 observed, 64.08 expected, observed/expected ratio (o/e) 0.45, 90% interval 0.34 to 0.62.
Homologues: Orthologues: macaque CLEC18A (96% identical), dog CLEC18C (80% identical), rat Clec18a (79% identical), mouse Clec18a (76% identical), Drosophila melanogaster CG42564 (18% identical), Caenorhabditis elegans scl-23 (15% identical), Caenorhabditis elegans scl-5 (13% identical), Caenorhabditis elegans scl-14 (13% identical), Caenorhabditis elegans scl-10 (12% identical), Caenorhabditis elegans scl-20 (12% identical), Drosophila melanogaster CG8483 (12% identical), Caenorhabditis elegans scl-12 (12% identical), and 36 more. Paralogues in human: CLEC18C (99% identical), CLEC18B (99% identical), CRISPLD2 (23% identical), CRISPLD1 (22% identical), CRISP1 (17% identical), CRISP3 (17% identical), CRISP2 (16% identical), R3HDML (16% identical), PI15 (15% identical), GLIPR1L1 (15% identical), GLIPR1L2 (14% identical), GLIPR1 (14% identical), and 1 more.
Diseases named in the same sentence as CLEC18A in open-access papers:
CLEC18A is named in the same sentence as 8 diseases in open-access papers, as found by Europe PMC text mining. Sharing a sentence is not in itself a finding about the gene and the disease. The quoted sentences say what the papers report.
viral infection (2 papers, 2021). "Our observation that CLEC18A acts as a TLR3 co-receptor is the first step to explore its potential role in innate immunity against viral infection, and more studies are necessary to understand how CLEC18A contributes to host innate immunity against viral infections in the future." (PMID 33603190, 2021). "Beyond hepatocytes, this isoform can also be secreted from monocytes, dendritic cells, and macrophages, suggesting that CLEC18A may be related to the innate immune system, and therefore may possibly participate in combatting viral infection." (PMID 33767710, 2021). "In human cell lines, CLEC18A stimulated Interferon-β1 expression following DENV infection (unpublished results of Yun-Ting Tsou), suggesting that CLEC18A may be a factor in PRR-mediated cytokine secretion and interferon-stimulating gene activation during viral infection." (PMID 33767710, 2021).
Autoimmunity (1 paper, 2023). The occurrence of an immune reaction against the organism's own cells or tissues. "We offer a novel molecular machinery with which to understand the association of HCV infection with autoimmunity and propose that CLEC18A may act as a candidate biomarker for HCV-associated MC." (PMID 37154715, 2023).
pterygium (1 paper, 2021). A wedge-shaped fibrovascular lesion arising from the bulbar conjunctiva and extending to the cornea. "We added 4 of the top upregulated genes in pterygium: CLEC18A, FOSL1, PPMN1 and SPRR3." (PMID 34769520, 2021).
infection (4 papers, 2021 to 2024). The state of being infected such as from the introduction of a foreign agent such as serum, vaccine, antigenic substance or organism. "The expression of CLEC18A-2xHA in the mosquito may therefore enhance anti-DENV activity following infection and result in a reduction in DENV viral load." (PMID 33767710, 2021). "Here, we tested the effect of CLEC18A expression on Aedes aegypti immune responses to infection." (PMID 33767710, 2021). "A single amino acid change from serine (S) to arginine (R) at position 339 within the CTLD of human CLEC18A has been shown to increase the binding affinity of toll-like receptor 3 (TLR3) and CLEC18A to poly(I:C), enhancing interferon (IFN) production against infection." (PMID 38764023, 2024).
tumor (3 papers, 2022 to 2025). "In mouse models of ccRCC, deletion of the mouse ortholog, Clec18a, resulted in enhanced tumor growth." (PMID 40847602, 2025). "Our results establish CLEC18A as a newly identified and critical regulator of ccRCC tumor growth and highlight the potential benefit of modulating expression of CLEC18 family genes in the renal tumor microenvironment." (PMID 40847602, 2025). "Besides, MST1R (AUC = 0.811), CAPG (AUC = 0.743), CLEC18A (AUC = 0.714), and EMT score (AUC = 0.700) also had significant diagnostic accuracy in distinguishing tumor and normal samples." (PMID 36072903, 2022). "The gene expression levels of CAPG, CLEC18A, and MST1R were higher in the tumor samples." (PMID 36072903, 2022).
CLEC18A also shares sentences with these, for which no sentence is quoted: atherosclerosis (1 paper); clear cell renal cell carcinoma (1); dengue (1).